S100A8 (S100 calcium binding protein A8)
Diseases named in the same sentence as S100A8 in open-access papers (continued):
Sharing a sentence is not in itself a finding about the gene and the disease.
oral cancer (8 papers, 2011 to 2023). "In OPSCC and oral cancer, S100A8/S100A9 is often downregulated, associated with lower tumor grading, upregulation of apoptosis-related genes, decreased EGFR expression, epithelial differentiation and decreased migration and invasion." (PMID 33469045, 2021). "After being tested on both oral cancer patients and healthy subjects, good specificity was proven through amperometric detection (IL-8 mRNA: −904 nA versus S100A8: −103 nA current; IL-8 protein: −298 nA versus IL-1 h protein: −50 nA)." (PMID 30769890, 2019). "Salivary S100A8 has been identified as a potential diagnostic biomarker for oral cavity infection or oral cancer; however, to date, no data are available regarding S100 protein expression in the saliva of patients with SLE." (PMID 35529863, 2022). "Despite the presence of S100A8 protein in 3 oral cell lines, only the increase of S100A9-positive cells in tumor stroma was significantly associated with poor differentiation and shortened recurrence-free survival of early-stage oral cancer patients." (PMID 26315114, 2015). "The PCR results showed that expression levels of EMT markers and genes related to metastasis such as S100A8 and S100A9 were significantly decreased after knocking down CD36 in oral cancer cells." (PMID 37207149, 2023).
preeclampsia (8 papers, 2013 to 2025). Preeclampsia is a hypertensive disorder of pregnancy that is characterized by new-onset hypertension with proteinuria presenting after 20 weeks of gestation, and depending on mild or severe forms may initially present with severe headache, visual disturbances, and hyperreflexia. "Our review aims to present an integrated view of the potential role of S100A8/A9 in the physiopathology of preeclampsia." (PMID 41155408, 2025). "According to a recent report, S100A8 levels in the peripheral blood are elevated in preeclampsia during pregnancy." (PMID 35892571, 2022). "Our identification of increased expression of LRRC27/42 and S100A8/9 in platelets of preeclampsia is also novel." (PMID 35455936, 2022). "The significantly increased concentrations of S100A8/A9 in amniotic fluid or in maternal serum have been reported in intra-amniotic inflammation, preterm labor and preeclampsia." (PMID 23290504, 2013). "Prospective studies are needed to determine whether S100A8/A9 measurement in placenta and plasma can offer independent information for preeclampsia." (PMID 41155408, 2025). "We speculate that S100A8/9 may be a target for antithrombotic treatment and could be used as a biomarker of preeclampsia and as an indicator of response to treatment." (PMID 35455936, 2022). "Therefore, it seems plausible that increased plasma S100A8/9 arising from leucocytes or activated platelets can contribute to platelet microaggregation in preeclampsia." (PMID 35455936, 2022). "Thus, S100A8/A9 might represent a useful plasmatic biomarker and therapeutic target in preeclampsia." (PMID 41155408, 2025). "Currently, S100A8 and S100A9 are gaining increased attention as inflammatory markers of preeclampsia." (PMID 41155408, 2025). "Previous studies have shown that S100A8/A9 expression is upregulated in the AF or maternal serum of pregnancies complicated by SPTB, HCA, IAI, and preeclampsia." (PMID 35130326, 2022). "A regression model using five RNAs selected for ‘pregnancy hypertension’ (preeclampsia and gestational hypertension) yielded good predictive power with an AUC of 0.86, and like the present study, their proposed RNA panel included NAMPT (the remaining markers were MMP8, SRPK1, S100A9, and S100A8)." (PMID 35741140, 2022). "Furthermore, S100A8 expression strongly correlates with IL-12, IL-6, and TNF-α and negatively correlates with IL-10, indicating that inflammatory cytokines and S100 protein interact during preeclampsia." (PMID 35892571, 2022). "Taken together, the potential roles of S100A8/9 and CXCL12/SDF-1α in thrombo-inflammation represent examples of how inflammation-driven/derived chemokines may modify platelet function and concomitantly contribute to the development and or progression of complications in preeclampsia." (PMID 35455936, 2022).
psoriatic arthritis (8 papers, 2006 to 2025). Joint inflammation associated with psoriasis. "In addition, as the serum level of S-calprotectin in patients with psoriatic arthritis increased, S100A8/9, which is associated with psoriatic arthritis pathogenesis, became a better predictor of ongoing disease than CRP or other pro-inflammatory cytokines." (PMID 29942307, 2018). "S100A8/ S100A9 alarmin is strongly expressed in the synovial sublining layers of psoriatic arthritis." (PMID 36700196, 2022). "In psoriatic arthritis patients, S100A8/A9 is intensely expressed in the synovial sublining layer, suggesting the importance of S100A8/A9 in mediating leukocyte migration across the endothelium." (PMID 29942307, 2018). "This study evaluated a synthetic KYNA analog’s effects on TNF-α, S100A8/9, S100A12, α-defensin, and interleukin-17 (IL-17) production and TSG-6 expression in ankylosing spondylitis (AS) and psoriatic arthritis (PsA)." (PMID 41465233, 2025). "S100 calcium-binding proteins like S100A8 and S100A9 play a role in regulating inflammation in psoriatic arthritis." (PMID 34108969, 2021). "The S100A8/A9 heterodimer has been shown to be a reliable indicator of disease activity and joint inflammation in inflammatory rheumatic diseases, including RA, juvenile RA (JRA), psoriatic arthritis, and spondylarthropathy." (PMID 16613612, 2006). "Our immunofluorescence studies showed the distribution of S100A8/A9-expressing macrophages in both the lining and sublining layer of RA ST, mostly corresponding with earlier studies of the expression pattern in the ST from RA, JRA, and psoriatic arthritis." (PMID 16613612, 2006). "Similarly, in Pa patients, S100A8 and S100A9 are expressed in skin lesions and present in elevated levels in the serum, and these proteins are also considered potential markers for psoriatic arthritis." (PMID 39877611, 2025).
skin cancer (8 papers, 2011 to 2025). "Nuclear localization of S100A8/A9 is also observed in breast and skin cancer tissues from patients, thereby providing clinical relevance of the observation in the ER-Src cellular model." (PMID 33523865, 2021). "Members of the larger S100 calcium-binding protein family, S100A8 and S100A9, regulate epithelial cell differentiation with increased expression of these proteins observed in inflammatory conditions and advanced stages of skin cancer." (PMID 28424693, 2017).
vasculitis (8 papers, 2009 to 2026). "Using lung histology and intravital imaging, we observed perivascular inflammation and large intravascular neutrophil aggregates in S100A8(Cre+) x Ptpn6fl/fl mice challenged with LPS or P. aeruginosa, suggesting that localized vasculitis may cause the observed pulmonary hemorrhage." (PMID 39352872, 2024). "We analyzed the cohort of 138 RA patients for associations between serum levels of S100A9, S100A8, S100A12 and sRAGE with RA clinical variables, CV risk factors, and with complications such as vasculitis, radiographic changes, and CV events." (PMID 19284577, 2009). "S100A8/A9 serum levels were shown to have significance in patients with other types of vasculitis." (PMID 38672106, 2024). "We believe that S100A8/A9 might be a potential biomarker of disease activity in this vasculitis." (PMID 38672106, 2024). "Original human studies investigating S100A8/9, S100A12, S100A4, and S100A10 in any form of vasculitis or related vascular inflammation were included." (PMID 41958648, 2026). "In the current study, we tried to investigate the role of S100A8/A9 and S100A12 in MPO-ANCA-positive vasculitis." (PMID 36088289, 2022). "In conclusion, the serum and urine levels of S100A8/A9 and S100A12 in patients with active MPO-ANCA-positive vasculitis were elevated and correlated with the severity of the disease." (PMID 36088289, 2022). "The raised levels of complement factors in the supernatant and the increased C5 expression of ANCA-activated neutrophils demonstrated that S100A8/A9 and S100A12 could promote the activation of the alternative complement pathway in MPO-ANCA-positive vasculitis." (PMID 36088289, 2022). "Simple linear regression analysis showed that serum sRAGE levels in RA patients were negatively associated with current smoking, family history of CV disease, history of vasculitis, diastolic blood pressure, RF, carriage of RAGE 82Ser, and serum levels of CRP and S100A8 (P < 0.05)." (PMID 19284577, 2009). "Over the past 20 years, S100A8, S100A9 and their complexes have emerged as very potent biomarkers of a wide range of inflammatory processes, including rheumatoid arthritis, juvenile idiopathic arthritis, inflammatory bowel disease, acute lung inflammation and vasculitis." (PMID 22489132, 2012).
acute kidney injury (7 papers, 2006 to 2025). Sudden and sustained deterioration of the kidney function characterized by decreased glomerular filtration rate, increased serum creatinine or oliguria. "In acute kidney injury, S100A8/A9 initiates and amplifies the inflammatory response, while S100A8/A9 blockade improves renal function, reduces inflammatory monocyte infiltration, and prevents long-term renal fibrosis." (PMID 38253716, 2024). "In clinical studies on patients (including pediatric patients) with acute kidney injury (AKI), DAMPs, specifically S100A8/S100A9 and urine mitochondrial DNA (mtDNA), have been identified as potential diagnostic and prognostic biomarkers, reflecting, for example, the severity of this disease." (PMID 40343200, 2025).
acute respiratory distress syndrome (7 papers, 2013 to 2025). Progressive and life-threatening pulmonary distress in the absence of an underlying pulmonary condition, usually following major trauma or surgery. "S100A8/A9 is a heterodimeric S100 protein released from leukocytes during inflammation, and plasma, leukocyte, or bronchoalveolar lavage levels correlate with disease activity in patients with septic shock or acute respiratory distress syndrome (ARDS)." (PMID 24089588, 2013). "S100A8/A9 levels are locally increased in acute respiratory distress syndrome patients and have been shown to play a role in neutrophil recruitment during ALI in mice." (PMID 35543413, 2022). "This study shows a link between S100A4, the S100A8/A9 heterodimer, and S100A10 and LDH levels, suggesting these molecules contribute to acute lung injury and ARDS (acute respiratory distress syndrome)." (PMID 35892571, 2022).
allergies (7 papers, 2014 to 2022). "The genes S100A8 and S100A9 are prominently up-regulated in inflammatory diseases being associated with phagocyte activation, like autoimmune and autoinflammatory disorders, infections, allergies, cardiovascular diseases and cancer." (PMID 35055093, 2022). "An elevated level of S100A8/A9 is not a prerequisite for inflammation but is associated with immunoregulatory factors induced by allergy-related factors." (PMID 33499808, 2021). "We examined the effects of S100A8 and S100A9 in HE subjects with CEL, HES, and reactive eosinophilia-induced allergies." (PMID 32903598, 2020). "S100A8 and S100A9 are important proteins in the pathogenesis of allergy." (PMID 32174780, 2020).
cholangiocarcinoma (7 papers, 2017 to 2025). A carcinoma that arises from the intrahepatic biliary tree (intrahepatic cholangiocarcinoma) or from the junction, or adjacent to the junction, of the right and left hepatic ducts (hilar cholangiocarcinoma). "S100A8 can activate the Toll-like receptor 4 (TLR4)-NF-κB signaling pathway, which upregulates VEGF expression, and thus, leads to the invasion and metastasis of cholangiocarcinoma cells." (PMID 39895787, 2025). "S100A8 overexpression in cholangiocarcinoma could facilitate in vitro and in vivo cell invasion and migration by activating the NF-κB pathway as well as increasing VEGF expression, while S100A8 knockdown or TLR4 and NF-κB inhibition could significantly inhibit cell migration and metastasis." (PMID 37701037, 2023).
chorioamnionitis (7 papers, 2012 to 2023). A morphologic finding indicating inflammation of the fetal sac membranes. "An upregulation of S100A8 is associated with chorioamnionitis/deciduitis." (PMID 33026626, 2020). "This implies a direct link between exposure to chorioamnionitis and an altered monocyte phenotype characterized by high expression of S100A8 and S100A9 genes." (PMID 32612607, 2020). "Our analysis included inflammatory mediators reported to be associated with chorioamnionitis, preterm labor, and fetal inflammatory response syndrome such as IL-1α, IL-1β, IL-6, TNF-α, S100A8, and S100A9." (PMID 22952869, 2012). "S100a8, S100a9, Il1b, and Mmp8 have been strongly associated with fetal inflammatory response syndrome (FIRS), preterm labor, and chorioamnionitis in preterm infants, further supporting our rat model using IA LPS injections to simulate IAI and a FIRS-like response." (PMID 38481391, 2023). "The S100A8/A9 protein dimer is elevated in neonatal sepsis in preterm infants, but to our knowledge, only one study has previously studied S100A8/A9 in preterm cord blood in association with chorioamnionitis and no changes were found." (PMID 32612607, 2020). "In spite of a relatively small study group and an arbitrary cut-off based on median expression of S100A8 and S100A9 only, we found a strong correlation between S100A gene expression and clinical conditions that are associated with chorioamnionitis and fetal inflammation." (PMID 32612607, 2020). "In this study, we investigate S100A8, S100A9, and S100A12 gene expression in cord blood monocytes from term healthy infants and preterm infants with exposure to chorioamnionitis or with a fetal inflammatory response." (PMID 32612607, 2020). "Increased levels of calgranulins S100A8, S100A9, and S100A12 have also been detected in the amniotic fluid of chorioamnionitis patients experiencing PTL and/or fetal inflammatory response syndrome." (PMID 22952869, 2012). "Disease outcome was assessed by microbial culture, in situ detection of U. parvum in fetal and utero-placental tissues, grading of chorioamnionitis, and placental gene expression of IL-1α, IL-1β, IL-6, TNF-α, S100A8, and S100A9." (PMID 22952869, 2012). "C57BL/6 infected animals predominantly exhibited mild to moderate chorioamnionitis (P<0.0001), and a significant reduction in placental expression of IL-1α, IL-1β, IL-6, TNF-α, S100A8, and S100A9 compared to sham controls (P<0.02)." (PMID 22952869, 2012). "Elevated levels of the S100A8/A9 protein dimer has previously been described in healthy term infants compared with preterm infants in the absence of exposure to chorioamnionitis or signs of infection." (PMID 32612607, 2020). "Based on our findings of S100A monocyte gene upregulation in association with clinical signs of inflammation, we investigated if S100A8 and S100A9 proteins in cord blood could serve as markers for exposure to chorioamnionitis and fetal inflammation." (PMID 32612607, 2020). "Conversely, severe protracted chorioamnionitis with cellular necrosis was the predominant lesion phenotype in BALB/c mice, which also exhibited a significant increase in placental expression of IL-1α, IL-1β, IL-6, TNF-α, S100A8, and S100A9 (P<0.01)." (PMID 22952869, 2012). "Protein levels of S100A8/A9 are increased in healthy term infants compared with adults and equal those found in adult patients during inflammation, while preterm infants not exposed to chorioamnionitis have lower levels than term infants, but still significantly higher than in adults." (PMID 32612607, 2020).
dry eye (7 papers, 2011 to 2021). "Among the proteins with altered expression, Prolactin-inducible protein was previously reported as reduced in dry-eye patients, while the protein S100A8 (calgranulin) was reported as increased in dry eye patients." (PMID 33372592, 2020). "Common ocular surface diseases such as dry eye, pterygium and corneal angiogenesis involve S100 family of proteins, particularly S100A8 and S100A936." (PMID 26423138, 2015). "In a study using the isobaric tagging for relative and absolute quantification (iTRAQ) technology, we found the S100A8 and S100A9 proteins were among a panel of 6 upregulated proteins found in the tear of dry eye patients." (PMID 26605353, 2014). "The average ratio of S100A8 and S100A9 in dry eye versus control subjects was 1.82 (SD 1.41) and 1.92 (SD 1.48) respectively." (PMID 26605353, 2014).
gout (7 papers, 2012 to 2024). A condition characterized by painful swelling of the joints, which is caused by deposition of urate crystals. "In gout patients, neutrophils migrate to gout-affected joints and secrete S100A8/A9, which accelerates inflammation." (PMID 29942307, 2018). "S100A8/A9 expression is significantly increased in synovia, tophi, and sera of gout patients and is correlated with disease progression." (PMID 29942307, 2018). "S100A8/A9 is increased in synovial fluid (SF), serum, and tophi of gout patients, while it is increased in the vitreous of PDR patients, which underlines the importance of appropriate specimen selection for the application of S100 proteins as biomarkers." (PMID 29942307, 2018). "In conditions such as gout, monosodium urate monohydrate crystals induce the release of S100A8/A9 from neutrophils and allow inflammatory attack by prolonging neutrophil life." (PMID 22363402, 2012). "MSU crystals promote neutrophils and macrophages that express and secrete S100A8/A9, and these S100 proteins enhance MSU-induced activation of the NLRP3 inflammasome in macrophages and neutrophils, which release IL-1β and mediate gout pain." (PMID 29942307, 2018).
ischemic stroke (7 papers, 2009 to 2025). A stroke disorder caused by obstruction of blood flow to the brain, due to thrombotic (local blood clot formation) or embolic (due to a blood clot or other material traveling from another site) event. "Systemic plasma levels of S100A8/A9 were associated with poor outcome in patients with moderate to severe ischemic stroke." (PMID 40656637, 2025). "Recently, scientists form China reported that increased plasma S100A8/A9 concentrations were significantly associated with poor prognosis at 3 months after ischemic stroke in 2 separate cohorts and pooled analysis of 4 785 patients." (PMID 37660166, 2023). "While our study demonstrates a strong association between elevated systemic plasma levels of S100A8/A9 and poor functional outcomes after ischemic stroke, it does not establish a causal relationship." (PMID 40656637, 2025). "The size of the brain damage after ischemia was indicated to be related to the S100a8 level in mice, whereas the elevated level of the S100A8/A9 heterodimer was indicated in human plasma after ischemia and was suggested to serve as a prognostic of ischemic stroke." (PMID 40332314, 2025). "Elevated levels of S100A8/A9 in venous blood samples have been correlated with functional outcome and increased 3-months mortality in patients with mild to moderate AIS suggesting its potential as a prognostic biomarker in human ischemic stroke." (PMID 40656637, 2025). "In addition, S100A8 constituted a novel COX-2 activator in microglia during neuroinflammation, indicating that S100A8 may be a new regulator of neuroinflammation under hypoxic conditions, which occurs in ischemic stroke." (PMID 33530496, 2021).
multiple sclerosis (7 papers, 2018 to 2024). A progressive autoimmune disorder affecting the central nervous system resulting in demyelination. "S100A8/A9, a heterodimer complex made up of calcium‐binding proteins S100A8 and S100A9, is markedly increased in the blood of multiple sclerosis patients." (PMID 36000202, 2022).